RNU6-599P (RNA, U6 small nuclear 599, pseudogene)
Gene: Small nuclear RNA gene on chromosome 9 (42,863,200 to 42,863,306, forward strand). Ensembl gene ENSG00000238529.
Homologues: Orthologues: chimpanzee U6 (98% identical), macaque U6 (93% identical), macaque U6 (92% identical), dog U6 (69% identical), mouse Gm54642 (62% identical), mouse Gm22279 (58% identical), rat LOC120101210 (57% identical). Paralogues in human: RNU6-1193P (99% identical), RNU6-1269P (99% identical), RNU6-368P (99% identical), RNU6-538P (99% identical), RNU6-1320P (98% identical), U6 (96% identical), U6 (95% identical), RNU6-316P (94% identical), RNU6-55P (94% identical), U6 (94% identical), RNU6-954P (93% identical), RNU6-821P (86% identical), and 1284 more.